S100A14 (S100 calcium binding protein A14)
Diseases named in the same sentence as S100A14 in open-access papers (continued):
Sharing a sentence is not in itself a finding about the gene and the disease.
breast carcinoma (continued). "Collectively, we identify S100A14 as an upstream regulator of CCL2/CXCL5 signaling and a metastatic driver of breast cancer." (PMID 32483412, 2020). "Previous studies have investigated role of LSR in breast cancer EMT, and S100A14 has been examined in pancreatic and cervical cancer." (PMID 28651527, 2017). "The second aim was to explore the molecular mechanisms by which S100A14 and S100A16 contribute to the progression of breast cancer." (PMID 25884418, 2015). "To further analyze the role of S100A14 and S100A16 proteins in breast cancer, we next examined the mRNA expression levels of S100A14 and S100A16 in human breast cancer cell lines by using qRT-PCR." (PMID 25884418, 2015). "All of these findings indicate that S100A14 and S100A16 expression augments the malignant phenotype of breast cancer." (PMID 25884418, 2015). "We investigated the interactions of S100A14, S100A16 with other binding protein(s) in breast cancer cells and examined the function of these molecules in cellular proliferation, migration and invasion." (PMID 25884418, 2015). "The first aim of the present study was to investigate the clinical significance of S100A14 and S100A16 expression in the prognosis of breast cancer patients." (PMID 25884418, 2015). "Since cellular localization of S100 proteins is important for their function, we performed a detailed analysis of the subcellular localization of S100A14 and S100A16 proteins in breast cancer cells." (PMID 25884418, 2015). "In an experimental study, the subcellular localization and function of these molecules was examined by using the human breast cancer cell lines MCF7 and SK-BR-3, both of which highly express S100A14 and S100A16 proteins." (PMID 25884418, 2015). "In a clinical study, an immunohistochemical analysis of S100A14 and S100A16 expression in archival specimens of primary tumors of 167 breast cancer patients was performed." (PMID 25884418, 2015). "Thus, we detected the serum levels of S100A14, CCL2 and CXCL5 in our prospective cohort of 150 breast cancer patients and 125 healthy controls." (PMID 32483412, 2020). "Indeed, the GEO database analysis demonstrated that the increased expression of S100A14, CCL2 or CXCL5 in primary breast cancer was a determinant of poor metastasis-free survival in patients." (PMID 32483412, 2020). "Our findings suggest that S100A14 and S100A16 protein expression may be predictive biomarkers for poorer prognosis of breast cancer patients." (PMID 25884418, 2015). "In addition, our findings indicate that S100A14 and S100A16 can promote invasive activity of breast cancer cells via an interaction with cytoskeletal dynamics." (PMID 25884418, 2015). "However, our multivariate analysis showed that expression of S100A14, and co-expression of S100A14 and S100A16, are independent prognostic factors for breast cancer." (PMID 25884418, 2015). "S100A14 and S100A16 might be prognostic biomarkers and potential therapeutic targets for breast cancer." (PMID 25884418, 2015). "The results showed that S100A14 had no significant influence on breast cancer cell proliferation." (PMID 32483412, 2020). "Because S100A14 and S100A16 can promote cancer cell motility and invasion via modulation of cytoskeletal dynamics, these proteins could be novel target molecules for therapeutic strategies in breast cancer patients." (PMID 25884418, 2015). "Thus, S100A14 and S100A16 proteins may promote the malignant nature of breast cancer by acting in cooperation with each other or with other binding proteins on the cell membrane." (PMID 25884418, 2015). "Thus, interaction between S100A14 and S100A16 proteins may be the reason for the strong correlation of their expression in human breast cancer tissues." (PMID 25884418, 2015). "This analysis revealed that S100A14 and S100A16 proteins were expressed mainly on the membrane of breast cancer cells, while no or faint staining was seen in normal epithelial cells of each sample (representative staining)." (PMID 25884418, 2015).
breast carcinoma (continued). "However, the S100A10 expression level was not highly noticeable in the invasive breast cancers in our in silico analysis; rather S100A11, S100A14, and S100P were markedly elevated in the cancer tissues compared to those in normal breast tissues." (PMID 38595825, 2024). "In addition, to our knowledge, clinicopathological studies of the expression of S100A16 (except for reports of global expression profiles), or of the co-expression of S100A14 and S100A16 in breast cancer patients have not been reported." (PMID 25884418, 2015).
pancreatic cancer (10 papers, 2017 to 2026). "We determined the genes that express differently in pancreatic cancer tissues compared with normal tissues and associate with survival (P < 0.05) as Hub genes, yielding a total of six Hub genes, including S100A14, KRT8, KRT19, MAL2, MYO5B, and PSCA." (PMID 36522691, 2022). "S100A14 was significantly highly expressed in pancreatic cancer cells and tissues and promoted progression in pancreatic cancer." (PMID 36522691, 2022). "Our results indicate that S100A14 is highly expressed both in mRNA and protein levels of pancreatic cancer." (PMID 34804125, 2021). "High expression of S100A14 was significantly correlated with advanced tumor stage and shorter overall survival in patients with pancreatic cancer." (PMID 34804125, 2021). "Gene expression microarray showed that the S100A14 expression in pancreatic cancer tissues was significantly higher than that in corresponding non-tumor tissues." (PMID 34804125, 2021). "S100A14 is an epithelial protein, expressed exclusively in epithelial pancreatic cancer cell lines, and repressed by ZEB1." (PMID 31123345, 2019). "Firstly, a pan-cancer analysis of S100A14 revealed that PC experienced one of the most remarkably increase of S100A14 expression among all types of cancer, which was also confirmed by qRT-PCR and western blot in pancreatic normal ductal cell line and pancreatic cancer cell lines." (PMID 35953822, 2022). "Overall, these pathways suggested that the function of S100A14 in pancreatic cancer may be related to the immunosuppressive tumor microenvironment in vivo." (PMID 35953822, 2022). "However, in pancreatic cancer tissue of patient 2, only S10010 and S100A14 are highly expressed compared with adjacent cancer." (PMID 34530774, 2021). "We investigated whether S100 proteins were associated with tumor grade, examined publicly available transcriptomic data from pancreatic cancer patients with high tumor purity, and confirmed the association of S100A4 with high-grade tumors and S100A14 expression with low-grade tumors." (PMID 36828915, 2023). "Additionally, analysis of a pan-pancreatic cancer cell line illustrated that S100A14 might inhibit CD8 + T cell activation via the upregulation of PD-L1 expression in PC cells, which was also verified by the immunohistochemical results of PUMCH cohort." (PMID 35953822, 2022). "However, the role of S100A14 in pancreatic cancer is rarely reported." (PMID 34530774, 2021). "Publicly available transcriptomic data from patients with pancreatic cancer and normal human pancreatic tissue also confirmed increased expression of both S100A4 and S100A14 in PDAC." (PMID 36828915, 2023). "Both S100A14 and S100A16 were up-regulated in pancreatic cancer, which was also verified in our experiments." (PMID 34530774, 2021). "However, in the pancreatic tumor array, correlations were observed between S100A6 and S100A11 (R = 0.49) and S100A14 (R = 0.45)." (PMID 37627239, 2023). "Therefore, the RNA-seq and proteomics data of all pancreatic cancer cell lines in the CCLE database were integrated and analyzed, which proved the expression of S100A14 was significantly positively correlated with the expression of PD-L1 in PC cell lines." (PMID 35953822, 2022). "Moreover, overexpression of S100A6, S100A10, S100A11, S100A14, and S100A16 may impair the infiltration and cytolytic activity of cytotoxic lymphocytes in pancreatic cancer." (PMID 36982351, 2023).
cervical carcinoma (9 papers, 2016 to 2024). A carcinoma arising from either the exocervical squamous epithelium or the endocervical glandular epithelium. "Overexpression of S100A14 is closely associated with the staging and lymph node metastasis of cervical cancer." (PMID 37978469, 2023). "Previous studies have found a correlation between S100A14 and the occurrence and progression of cervical cancer." (PMID 37978469, 2023). "S100A14 has been shown to promote cell cycle progression, cell growth, migration, and invasion of cervical cancer cells." (PMID 37978469, 2023). "There are many subtypes of S100 calcium-binding protein, and several studies have found that S100A7, S100A9, S100A11, and S100A14 are closely related to cervical cancer." (PMID 36230965, 2022). "Further, S100A14 was shown to enhance epithelial mesenchymal transition of cervical cancer cells as evidenced by the upregulation of N-cadherin and Vimentin, and downregulation of E-cadherin." (PMID 31105881, 2019). "The modulation of S100A14 correlated positively with increased proliferation, migration and invasion of cervical cancer cells in vitro." (PMID 31105881, 2019). "Similarly to S100A2 and S100A11, S100A14 appears to have a complex role in cancer, showing overexpression in breast, liver and cervical cancer, but downregulation in other cancers such as rectal, kidney, colon and esophageal cancers." (PMID 37627239, 2023). "Similar to S100A14, the expression of S100A7 was also significantly upregulated in cervical cancer tissues compared with normal cervical tissues." (PMID 36230965, 2022). "Our previous study has shown that S100A14 can act as a mediator of EMT and promote cervical cancer cell migration and invasion." (PMID 28212564, 2017).
lung carcinoma (8 papers, 2017 to 2025). "S100A14 is differentially expressed in various cancers, downregulated in gastrointestinal tumors, and upregulated in ovarian, breast, and lung cancers." (PMID 40806532, 2025). "Analogously, genes involved in wound healing and cell migration (i.e., SERPINE1, HMGCR, IGFBP5, and S100A14) or reported as prognostic factors in breast, ovarian, gastric, and lung cancers (i.e., MAPRE1, HSPA1B, and PPME1) were negatively modulated." (PMID 31752957, 2019). "Finally, in pilot experiments conducted on stimulated saliva from a patient with a lung cancer nodule, we detected altered content or selective presence of proteins involved in lung carcinogenesis, such as serpin B3 or the proteins S100A14 and aldoketoreductase-A1, respectively." (PMID 40869249, 2025). "Indeed, and just for example, we detected the upregulation of SERPB3 as well as the exclusive presence of S100A14 and AKR1A1 proteins in the saliva of this patient, which have already been implicated in LC and could represent potential lung cancer biomarkers." (PMID 40869249, 2025). "In lung cancer cells, HIF1A-AS2 was the sponge for miR-153-5p, and miR-153-5p targeted S100A14; thus, HIF1A-AS2 promoted S100A14 expression by regulating miR-153-5p." (PMID 35328496, 2022). "In support of this line of thinking are also findings from in vitro models of another epithelial malignancy which revealed that treatment with 5-aza-2’deoxycytidine could not induce re-expression of S100A14 mRNA in eight lung cancer cell lines." (PMID 31105881, 2019).
ovarian carcinoma (8 papers, 2014 to 2021). A malignant neoplasm originating from the surface ovarian epithelium. "Investigation of the underlying signaling pathway revealed that S100A14 might contribute to epithelial ovarian cancer progression via PI3K/Akt pathway." (PMID 31105881, 2019). "However, the role of S100A14 in ovarian cancer development and its underlying molecular mechanisms remain unclear." (PMID 24939856, 2014). "In addition to traditional pathological factors (such as nodal stage, presence of metastasis and tumour grade), determining the presence of molecular markers (CYTH3 and S100A14) may allow us to more adequately assess a patient’s risk of developing chemoresistance in ovarian cancer." (PMID 34413360, 2021). "Overall, S100A14 has been reported to be overexpressed in ovarian cancers as compared to the normal control tissues." (PMID 31105881, 2019). "The authors reported increased cell proliferation, colony and sphere formation abilities, and migration and invasion of epithelial ovarian cancer cells upon S100A14 over-expression." (PMID 31105881, 2019). "By using lentiviral-mediated expression and knock-down strategies, Cho and coauthors have investigated the role of S100A14 in the malignant phenotype of epithelial ovarian cancer cells." (PMID 31105881, 2019). "In particular, increased expression of S100A1, S100A4, S100A7, and S100A14 has been documented in multiple cancers including ovarian cancer." (PMID 31739800, 2019). "Ovarian cancer specimens with positivity or upregulation of S100A14 have been correlated with advanced stage, poor tumor grade, tumor recurrence, resistance to platinum-based therapy and shorter survival probabilities." (PMID 31105881, 2019). "To further analyze S100A14 expression in ovarian cancer, we combined seven microarray data sets (GSE55510, GSE55512, GSE27651, GSE14001, GSE14407, GSE28724, and GSE51373) downloaded from the GEO database according to the literature." (PMID 24939856, 2014). "As expected, we found that S100A14 mRNA expression was significantly higher in ovarian cancer (n = 149) than in normal ovarian surface epithelium (n = 29) (P < 0.001)." (PMID 24939856, 2014). "Enhanced S100A14 expression correlated positively with clinicopathological parameters in both in vitro and in vivo ovarian cancer systems, lending support for the use of S100A14 to determine clinicopathological stage and/or prognosis in ovarian cancer." (PMID 24939856, 2014). "In the present study, we investigated the functional role and clinical significance of S100A14 expression in ovarian cancer using EOC cell lines and mouse xenograft models." (PMID 24939856, 2014). "In this study, we investigated the significance of S100A14 expression in epithelial ovarian cancers (EOCs) as well as it's mechanism of action." (PMID 24939856, 2014). "In addition, over-expression of S100A14 mRNA and protein in ovarian cancer cell lines as compared to human ovarian surface epithelial cells has been reported." (PMID 31105881, 2019). "Further study of S100A14's molecular mechanisms may lead to the development of a novel therapeutic target for ovarian cancer." (PMID 24939856, 2014). "Among various genes and proteins previously identified to be expressed or modified in ovarian cancer, S100A14 attracted research interest due to its marked and consistent overexpression in all six EOC cell lines and its reported role in cell growth and survival in other cancers." (PMID 24939856, 2014). "Specifically for ovarian cancer, the prior studies of S100A14 on SOC demonstrated that S100A14 was overexpressed in transformed cells on both the RNA and protein levels, which is consistent with our results." (PMID 27270322, 2016). "Reverse transcriptase-PCR (RT-PCR) and real-time PCR revealed thatS100A14 mRNA levels were abundantly expressed in ovarian cancer cell lines, except TOV112D, OVCA433, and YDOV-151, whereas S100A14 expression was almost undetectable in HOSE cell lines." (PMID 24939856, 2014).
colorectal cancer (6 papers, 2009 to 2025). A primary or metastatic malignant neoplasm that affects the colon or rectum. "In line with the mRNA data from RT-PCR, S100A14 immunohistochemistry showed downregulation or loss of S100A14 expression in majority (56.5%) of colorectal cancer." (PMID 31105881, 2019). "Furthermore, S100A14 has been implicated in the differentiation process of gastric tumor cells and, more recently, its ability to reduce stemness in colorectal cancer cell lines has been established." (PMID 40806532, 2025). "Collectively, our results demonstrate for the first time that S100A14 is a potential biomarker of serrated neoplasia and further suggests its potential role in predicting immunotherapy responses in colorectal cancer." (PMID 40806532, 2025). "Gene expression analyses of public datasets showed higher S100A14 expression in BRAFV600E-mutated and MSI-H colorectal cancers compared to microsatellite stable BRAFwt tumors." (PMID 40806532, 2025). "The author reported a substantial expression of S100A14 in different human colorectal cancer cell lines (SW840, SW620, LoVo and HT29)." (PMID 31105881, 2019). "Three proteins identified by MR, S100A16, S100A14 and PDE5A, might share causal variables with HER-positive breast cancer and colorectal cancer." (PMID 38762700, 2024). "In summary, our study highlights differential S100A14 abundance and expression in lesions known to originate from the conventional adenoma–carcinoma sequence from those resulting from the serrated transformation sequence, including sessile serrated lesions up to colorectal cancer." (PMID 40806532, 2025). "Interestingly, the results of colocalization analysis showed that S100A16 (coloc, PP.H4.abf = 0.933), S100A14 (coloc, PP.H4.abf = 0.913), and PDE5A (coloc, PP.H4.abf = 0.855) had the shared causal variation with HER-positive breast and colorectal cancers, respectively." (PMID 38762700, 2024). "In colorectal cancer, S100A14 has been found to be downregulated in tumors compared to normal tissues, and its low expression has been associated with poorer patient prognosis." (PMID 40806532, 2025). "We hypothesize that S100A14 may play a role in shaping the anti-tumor immune microenvironment characteristic of SSL and MSI-H colorectal cancers, potentially serving as both a therapeutic target and a prognostic biomarker for predicting immunotherapy response." (PMID 40806532, 2025). "Ultimately, based on our analysis, S100A16 and S100A14 were validated as potential second-class drug targets for HER-positive breast cancer, PDE5A as potential first-class drug targets for colorectal cancer, and MIA as potential second-class drug targets for non-small cell lung cancer." (PMID 38762700, 2024).
lymph node metastasis (6 papers, 2015 to 2024). "Correspondingly, the TCGA database analysis demonstrated that S100A14 expression is significantly associated with lymph node metastasis." (PMID 32483412, 2020). "Multiplex immunohistochemistry (mIHC) staining of 4 MISs (CD44, S100A14, RHOD, and TACSTD2) in ESCC clinical samples demonstrated differential MIS expression scores (dMISs) predict lymph node metastasis, overall survival, and risk of carcinothrombosis." (PMID 38864342, 2024). "Co-expression of S100A14 and S100A16 was correlated with younger patient age (<60 years old,P= 0.025), lymph node metastasis (P= 0.005), ER-negative status (P= 0.008) and HER2-positive status (P < 0.001)." (PMID 25884418, 2015).
esophageal squamous cell carcinoma (5 papers, 2011 to 2024). Esophageal squamous cell carcinoma (ESCC) is a type of esophageal carcinoma (EC) that can affect any part of the esophagus, but is usually located in the upper or middle third. "Here we investigated the effects of S100A14 on esophageal squamous cell carcinoma (ESCC) cell lines." (PMID 21559403, 2011). "CD44, TACSTD2, S100A14, and RHOD act as signatures to represent cancer‐spreading‐initiating cells in esophageal squamous cell carcinoma." (PMID 38864342, 2024). "The extracellular S100A14 was shown to bind with RAGE leading to the activation of mitogen activated protein (MAP) kinase (extracellular signal-regulated kinase, ERK) and NF-κB signaling pathways, thereby promoting cell proliferation and survival in esophageal squamous cell carcinoma (ESCC)." (PMID 31105881, 2019).